IL17D (interleukin 17D)
Diseases named in the same sentence as IL17D in open-access papers (continued):
Sharing a sentence is not in itself a finding about the gene and the disease.
tumor (continued). "Moreover, forced expression of IL-17D in edited tumor cells induced rejection by stimulating MCP-1 production from tumor endothelial cells, resulting in the recruitment of natural killer (NK) cells." (PMID 29548303, 2018). "Moreover, activating Nrf2 to induce IL-17D in established tumors led to NK cell-dependent tumor regression." (PMID 29548303, 2018). "Moreover, forced expression of IL-17D in edited tumor cells induced rejection by stimulating MCP-1 production from tumor endothelial cells, leading to the recruitment of NK cells." (PMID 25590298, 2015). "However, forced expression of IL-17D in edited mouse tumor cells induced rejection by leading to the recruitment of NK cells." (PMID 25152827, 2014). "However, forced expression of IL-17D in edited mouse tumor cells induced rejection by propitiating recruitment of NK cells." (PMID 25152827, 2014). "In our results, it is confirmed that the expression of IL-17A, IL-17B, IL-17C, IL-17D, IL-17E (IL-25), and IL-17F in tumor immune subtypes is statistically significant, especially in BRCA; there may be a potential microenvironmental regulation mechanism that remains to be investigated." (PMID 36159856, 2022). "Taking into account the propensity of IL-17A to propel tumor growth either in an autocrine or paracrine fashion, findings on IL-17D suggest that this cytokine counterbalances the pro-tumor activity of Th17 cells and IL-17A, and strategies to increase IL-17D might find clinical application." (PMID 33244315, 2020). "IL‐1RA and IL‐1β were detected in shed tumor cells from the treated patients, as well as IFN‐α2 and IL‐17D." (PMID 38553868, 2024). "To examine the effect of IL-17D expression on tumor growth in vivo, we subcutaneously injected LLC1 cells into 8-week-old C57BL/6 mice and measured the tumor size every 3 days." (PMID 35939336, 2022). "SORBS2 can stabilize the tumour-suppressive immunomodulatory transcripts WAP four-disulfide core domain 1 (WFDC1) and interleukin-17D (IL-17D), thereby suppressing metastatic colonization of OC cells." (PMID 35062979, 2022). "A total of 30 IL22RA1-correlated genes (e.g. IL17D, IL22RA2, IL20RB, IL10RA, IL10RB, TSLP and TYK2) are involved in the JAK/STAT pathway which promotes tumor progression." (PMID 35874683, 2022). "To further study whether blocking IL-17D influences tumor progression via promoting TAM infiltration, we treated animals with an IL-17D antibody in subcutaneous mouse models." (PMID 35939336, 2022). "Moreover, cytokines and growth factors such as TGFB1, IL‐6 and IL‐17D can increase the interplay between MDSC and Th17 cells in tumor microenvironment." (PMID 33107145, 2021). "An advantage of such compound is that it activates the tumor autocrine Nrf2/IL-17D signaling, by inducing cellular stress without producing reactive oxygen species." (PMID 33244315, 2020). "IL-17D-induced recruitment attracted mostly CD27high NK cells, a semi-mature population of NK cells participating in IFN-γ-dependent T cell priming and contributing to suppressing tumor progression." (PMID 33322371, 2020). "Furthermore, cytokine interleukin 17D (IL-17D) was highly expressed in certain unedited tumors but not in edited mouse tumor cell lines." (PMID 25590298, 2015). "Therefore, it is conceivable that WFDC1 and IL-17D, as part of a SORBS2-stablized secretome, could play a crucial role in modulating the polarization of myeloid cells within the tumor microenvironment, which remodel it towards a tumor-suppressive immune milieu." (PMID 29548303, 2018).
infection (14 papers, 2012 to 2026). The state of being infected such as from the introduction of a foreign agent such as serum, vaccine, antigenic substance or organism. "We also identified immune/inflammatory response markers associated with aGVHD (IL-9, Eotaxin-3), cGVHD (Flt-1), infection (D-dimer), or relapse (IL-17D, bFGF, Eotaxin-3)." (PMID 35700185, 2022). "We have previously shown that IL-17D-deficient mice displayed sub-optimal responses to infection by MCMV and local vaccinia virus (VV) scarification." (PMID 30209334, 2018). "Infection with group A Streptococcus in both wild-type and IL-17D-deficient mice (il17d–/–) revealed that IL-17D knockout mice experienced greater weight loss, reduced survival rates, and a greater bacterial load in the kidneys and peritoneal cavity after infection." (PMID 40536951, 2026). "Similarly, we observed that Rag1−/− and Rag1−/− x Il17d−/− mice exhibited comparable weight loss and HA expression after infection with influenza A virus with similar viral load in lung." (PMID 31244826, 2019). "Also, our study contradicts previous reports describing the enhanced degree of infection in mice harboring IL-17D deficiency." (PMID 31244826, 2019). "During infection, the loss of IL-17D resulted in compromised CD8 T cell activity." (PMID 31244826, 2019). "Surprisingly, recent reports have shown that IL-17D can promote pathogen infection by inhibiting the activity of CD8+ T cells." (PMID 40536951, 2026). "Following electroceutical treatment, anti-infection genes such as Il10ra and Foxp3 were up-regulated, whereas genes promoting immune response and metabolism, including Il17d and Map3k7, were down-regulated." (PMID 39951521, 2025). "In fish, several IL-17 family members—such as IL-17A/F2a, IL-17C1, IL-17C2, and IL-17D—have been identified and shown to be responsive during infection." (PMID 40943072, 2025). "Interleukin-17D (IL-17D), a member of the IL-17 family of cytokines, plays an important role in the host defense against infection and inflammation." (PMID 35939336, 2022). "Although we do not know how the basal expression levels are modified by the injection process, the infection with the pathogenic NNV up-regulates the IL-17C1 transcription in both HK and brain, and the IL-17D in the brain." (PMID 32244562, 2020). "To better understand how IL-17D promotes pathogenicity in infection, we focused on LM-OVA infection, as it is relatively straightforward to dissect its cellular mechanism." (PMID 31244826, 2019). "A cellular analysis on day 7 after infection indicated that there was an enhanced antigen-specific CD8 (OT1 peptide) immune response in Il17d−/− mice while CD4 (LLO peptide) response was similar between WT and Il17d−/− mice." (PMID 31244826, 2019). "IL-17D compromises host immunity during infection by suppressing DCs to modulate CD8 T cell activity." (PMID 31244826, 2019). "To ensure the reduction of IL-17D upon the infection occurs in protein level as well, we measured IL-17D using ELISA from total lysates of liver tissue before and after the infection." (PMID 31244826, 2019). "We discovered that, during infection, IL-17D controls the magnitude of CD8 T cell responses in part by suppressing DCs." (PMID 31244826, 2019). "Since IL-17D promotes pathogenicity during infection and suppresses CD8 T cell activity, we examined the cellular compartments of IL-17D production." (PMID 31244826, 2019). "Herein, we show that early immune cell accumulation at the peritoneal site of infection by mouse cytomegalovirus (MCMV) is mediated by IL-17D." (PMID 30209334, 2018). "In the SS2 infection, IL17D was elevated by 2.07-fold, which can stimulate production of IL6, IL8, and GM-CSF production in endothelial cells." (PMID 25906258, 2015). "Our study provides a further rationale for understanding each cytokine in its own disease-specific setting and suggests that the therapeutic blockage of IL-17D may improve host defense during infection." (PMID 31244826, 2019).
infection (continued). "IL-17D protein expression was reduced after the infection similar to mRNA expression." (PMID 31244826, 2019). "However, it is possible that cellular mechanisms other than DCs/CD8 T cells mediate the role of IL-17D compromising host defense during infection." (PMID 31244826, 2019). "To determine whether IL-17D generally promotes pathogenicity during infection, we challenged WT and Il17d−/− mice with PR8 influenza A virus." (PMID 31244826, 2019). "In summary, our findings demonstrate that IL-17D regulates protective immunity against infections." (PMID 31244826, 2019). "While the mechanisms remain unclear, the downregulation of IL17D or IL-27 (also downregulated in acute infection) might partially explain the reduced IL-8 expression observed later in infection." (PMID 22511950, 2012). "By contrast, the infection of sea bass juveniles with nodavirus (NNV), a very pathogenic virus for this fish species, resulted in the up-regulation of the transcription of IL-17C1 in the head-kidney and of IL-17C1 and IL-17D in the brain, the target tissue for NNV replication." (PMID 32244562, 2020). "Notably, in the absence of adaptive immune cells, IL-17D deficiency no longer provided its protective immunity after infection, indicating that IL-17D compromises its anti-bacterial and viral immunity by suppressing adaptive immunity." (PMID 31244826, 2019). "In sharp contrast, IL-17A/F1, IL-17A/F2, IL-17C2, and IL-17D transcription was inhibited in the HK, while IL-17A/F1 and IL-17A/F3 did in the brain upon NNV infection." (PMID 32244562, 2020). "This property of IL-17D suppressing DC activity, leading to CD8 T cell suppression, distinguishes IL-17D from other IL-17 family cytokines that are host protective during infection." (PMID 31244826, 2019). "Eight genes (NCF4, CD14, IL17D, CD1D, CD163, IL1R2, TLR9, and TLR2) with different expression in each infection group were selected for qPCR analysis." (PMID 25906258, 2015). "In conclusion, IL-17D plays a comprehensive regulatory role in anti-infection and antitumor by relying on immune cells, rather than simply promoting or inhibiting the development of disease." (PMID 35071607, 2022). "We found that IL-17D from the non-hematopoietic compartment regulates protective immunity during infection." (PMID 31244826, 2019). "Furthermore, IL-17D could be repressed upon LM-OVA infection, although we cannot rule out the possibility that the IL-17D-producing cell type is less represented in the CD45-negative fraction upon infection." (PMID 31244826, 2019).
cancer (13 papers, 2015 to 2024). A tumor composed of atypical neoplastic, often pleomorphic cells that invade other tissues. "As for IL-17A, the role of IL-17B, IL-17C, IL-17D, IL-17E, and IL-17F in cancer remain controversial." (PMID 33244315, 2020). "Enhanced expression of either WFDC1 or IL-17D potently represses SORBS2 depletion-mediated cancer metastasis promotion." (PMID 29548303, 2018). "We have recently shown that the understudied cytokine Interleukin (IL)-17D can mediate neutrophil, natural killer (NK) cell and monocyte infiltration in sterile inflammation and cancer." (PMID 30209334, 2018). "When comparing RM with PC, we identified key regeneration-related genes APOD and IBSP, along with several significant pathways: cAMP signaling pathway (HHIP), cytokine-cytokine receptor interaction (IL17D), pathways in cancer (HHIP, DAPK2), and biosynthesis of cofactors (RDH12, HAAO)." (PMID 39684926, 2024). "Since animals lacking in IL-17D showed increased development of MCA-induced tumors and worsened pathology when infected with vaccinia virus (VV) or murine cytomegalovirus (MCMV), IL-17D production is necessary for efficient cancer surveillance and antiviral responses." (PMID 37946175, 2023). "The IL-17 family of cytokines is composed of six members named IL-17A (commonly known as IL-17), IL-17B, IL-17C, IL-17D, IL-17E (also known as IL-25), and IL-17F with different sequence homology and functions that are important players in host defense responses, inflammation, and cancer development." (PMID 38068860, 2023). "Thus, IL-17D should contribute to protecting us from viruses and cancer." (PMID 33244315, 2020). "Specifically, we focused on the pro-cancer immunomodulatory role of SORBS2 and its bound targets WFDC1 and IL-17D." (PMID 29548303, 2018).
bacterial infection (2 papers, 2019 to 2025). "Previous studies have shown IL-17A/F, IL-17B, IL-17C, IL-17D and IL-17N could stimulate the expression of proinflammatory cytokines, chemokines and antimicrobial peptides in response to bacterial infection." (PMID 40149405, 2025).
IL17D also shares sentences with these, for which no sentence is quoted: glioma (2 papers); adenocarcinoma (1); adenosquamous carcinoma (1); asthma (1); Cardiovascular disease (1); cognitive decline (1); cognitive deficits (1); gastric cancer (1); heart failure (1); influenza infection (1); large cell carcinoma (1); lymphoma (1); mastitis (1); Obesity (1); pharynx squamous cell carcinoma (1); Primary microcephaly (1); sarcoma (1); skin inflammation (1); squamous cell carcinoma (1).